INS (insulin)
Diseases named in the same sentence as INS in open-access papers (continued):
Sharing a sentence is not in itself a finding about the gene and the disease.
type 2 diabetes (continued). "By contrast, physical inactivity is considered a potential risk factor for type 2 diabetes and other metabolic diseases, whereas exercise (particularly endurance exercise training) may enhance fat oxidation, which is associated with insulin sensitivity improvement in patients with obesity." (PMID 32260278, 2020). "The insulin-sensitizing, anti-inflammatory, and anti-atherogenic effects of adiponectin makes it a critically vital molecule to study in survivors, as it may serve as a biomarker of future cardiovascular and type 2 diabetes risk." (PMID 33122755, 2020). "Type 2 diabetes (T2D) is associated with insulin resistance i.e., the inability of tissue cells to respond to insulin." (PMID 32582175, 2020). "Numerous studies in Caucasian populations suggest that vigorous exercise intensity may promote greater improvements in CRF and other type 2 diabetes risk factors (e.g., reduction of glucose/insulin levels, pulse wave velocity, and body fat) than moderate intensity." (PMID 31395096, 2019). "Because type 2 diabetes causes the destruction of pancreatic β-cells via oxidative stress and decreases insulin secretion, the ability of high-fat-diet-fed diabetic mice to secret insulin was reduced, and the high concentration of BMLE (600 mg/kg) significantly restored insulin secretion." (PMID 30841887, 2019). "Therefore, moderate levels of exercise (2 h per week), independent of exercise modality, may be associated with significant improvements in insulin sensitivity and resistance in youth with Type 2 Diabetes." (PMID 30621667, 2019). "As the HbA1c-associated miRNAs were strongly associated with the gene expression of the target mRNAs in insulin signaling and type II diabetes mellitus pathways, it can be hypothesized that long-term glucose levels in particular can affect gene expression via miRNA regulation." (PMID 31222113, 2019). "Understanding the physiological basis for elevated post-prandial insulin secretion after bariatric surgery is therefore important both for preventing hypoglycemia in susceptible post-surgical populations and for developing new therapeutic strategies to treat type 2 diabetes." (PMID 30726726, 2019). "Type 2 diabetes (T2DM) belongs to the group of metabolic diseases, which are directly caused by a secretion disorder and/or abnormal insulin action—a key hormone in maintaining the energy homeostasis of the body." (PMID 31195747, 2019). "In fact, type II diabetes is a major risk factor for dementia and has been directly associated with the Aβ accumulation in the brain, due to deficient brain Aβ clearance resulting from the competition between insulin and the Aβ for binding to the insulin-degrading enzyme." (PMID 31291963, 2019). "For example, in type-2 diabetes, the concomitant increase in erythrocyte membrane stiffness can reduce the microcirculatory flow and cause tissue hypoxia and insufficient tissue nutrition, and lipid molecules can affect glucose transport by insulin-independent GLUTs and in turn glucose efficiency." (PMID 31030467, 2019). "Type 2 diabetes mellitus (T2DM) is a comprehensive metabolic disease caused by insufficient insulin secretion or insulin resistance and is associated with a variety of systemic complications." (PMID 31781013, 2019). "However, DNAm PAI-1 stands out when it comes to associations with type 2 diabetes status, glucose-, insulin-, triglyceride levels, anthropometric measures of adiposity (body mass index and waist-to-hip ratio), and computed tomography data on fatty liver and excess adipose tissue." (PMID 30669119, 2019). "Conversely, children who receive type 2 diabetes susceptibility alleles from their parents are less sensitive to insulin and therefore tend to have lower birthweights on average, resulting in an inverse association of birthweight with subsequent type 2 diabetes (Fetal Insulin Hypothesis)." (PMID 30815700, 2019).
type 2 diabetes (continued). "Type 2 diabetes mellitus (T2DM) is a chronic disease, caused when the body is unable to effectively use insulin to maintain blood glucose levels." (PMID 29495492, 2018). "There is evidence that insulin regulates glucose metabolism in PMNs and is responsible for the activation of its main functions which may be altered by the IR associated with either obesity or type 2-diabetes." (PMID 30005063, 2018). "In fact, a systematic review aiming to identify factors associated with adherence to insulin therapy in type 1 and type 2 diabetes showed that adherence is generally poor and suggested that more flexible regimen may improve it as well as facilitating insulin deliver by switching to a pen device." (PMID 29636825, 2018). "SFRP5 suppresses chronic inflammation and can consequently improve insulin sensitivity, highlighting its role as an independent risk factor for type 2 diabetes mellitus (T2DM), with a notably important role in the maintenance of glucose homeostasis." (PMID 29789397, 2018). "Examination of Pbx1+/− mice has also shown that this transcription factor is required for pancreatic insulin secretion in mature islets, as Pbx1 inactivation causes reduction of circulating insulin levels and impaired glucose tolerance, conditions known to presage the onset of overt type 2 diabetes." (PMID 30002646, 2018). "We hypothesised that by improving insulin sensitivity, podocytes would be protected from ER stress, with the corollary that the reduced insulin sensitivity in type 2 diabetes would predispose podocytes to ER stress, increasing GFB permeability and promoting DN." (PMID 29500363, 2018). "Increased oxidative stress and various pro-inflammatory cytokines and chemokines, including tumor necrosis factor-α (TNF-α) and interleukin-6 (IL-6), which might interfere with anti-inflammatory effects on insulin action, were associated with insulin resistance, obesity, and type 2 diabetes." (PMID 30532735, 2018). "Most experimental studies on the progression of glucose intolerance towards type 2 diabetes have focused on the associated beta cell dysfunction, rather than the early gain-of-function of beta cells that sustain whole-body glucose homeostasis via increased insulin secretion." (PMID 30166558, 2018). "The cardiovascular safety of insulin degludec compared with insulin glargine U100 has recently been studied in the Double-blinded Trial Comparing Cardiovascular Safety of Insulin Degludec vs Insulin Glargine in Patients with Type 2 Diabetes at High Risk of Cardiovascular Events (DEVOTE)." (PMID 28913575, 2018). "Type 2 diabetes Mellitus (T2DM) is associated with impaired insulin signalling, leading to hyperglycaemia and micro and macrovascular diseases." (PMID 30250013, 2018). "Type 2 diabetes (T2D) is a high-risk factor for Alzheimer’s disease (AD) due to impaired insulin signaling pathway in brain." (PMID 28225806, 2017). "Insomnia can be effectively treated and may be a promising avenue for interventions to reduce type 2 diabetes incidence, as there are plausible biological mechanisms linking sleep loss to the development of type 2 diabetes via increases in insulin resistance and appetite." (PMID 28302102, 2017). "Type 2 diabetes mellitus (T2DM) is a chronic condition that results from a progressive insulin secretory defect related to insulin resistance caused by a combination of genetic and lifestyle factors." (PMID 28929119, 2017). "This study shows that SNAP-25b-deficiency results in increased insulin release, higher number of β cells in males, altered islet size, lost collective control of Ca2+-oscillations and defective inter-β-cell-connectivity within islets, all features of the early phase of developing type 2 diabetes." (PMID 28798351, 2017).
type 2 diabetes (continued). "Reduced insulin sensitivity is the pathophysiologic basis of type 2 diabetes and may underlie a host of metabolic and cardiovascular disorders including glycaemic abnormality, dyslipidemia, hypertension and abdominal adiposity, which comprise the basis of the metabolic syndrome." (PMID 28912840, 2017). "This supports the Fetal Insulin Hypothesis and reflects a general pattern for type 2 diabetes susceptibility alleles: genome-wide, there is an inverse genetic correlation with birth weight, and initial estimates suggest genetic factors explain a large part of the covariance between the two traits." (PMID 28293907, 2017). "In the context of obesity and type 2 diabetes mellitus (T2DM) management, protein intake has revealed interesting positive effects on glycemia decrease, insulin secretion, and body fat loss." (PMID 28484425, 2017). "Relative or absolute deficiency of insulin-producing β cells in pancreatic endocrine islets underlies the pathogenesis of both type 1 and type 2 diabetes mellitus (T1D and T2D, respectively)." (PMID 28851992, 2017). "This is one of the key etiological factors underlying the development of type 2 diabetes mellitus (T2DM), primarily due to the fact that it facilitates resistance to insulin." (PMID 28386310, 2017). "This case-control study was designed to investigate the gene expression profile in skeletal muscle from severely insulin resistant patients with long-standing type 2 diabetes (T2D), and to determine associated signaling pathways." (PMID 28252104, 2017). "Thus, the appearance of insulin-deficient islets constitutes the main morphological criterion able to distinguish type 1 diabetic pancreases from type 2 diabetic pancreases, even though the loss of beta cells in type 1 diabetes varies greatly, especially at the onset of disease." (PMID 27796420, 2017). "As our results suggest a potential important causal role of fasting insulin, the occurrence of hyperinsulinemia in early type 2 diabetes would also be in line with insulin acting as a confounder for any observed association between type 2 diabetes and pancreatic cancer risk." (PMID 28954281, 2017). "In particular, the finding that podocytes isolated from db/db mice display reduced insulin-stimulated Akt phosphorylation may suggest that circulating factors, associated with type 2 diabetes, have the capacity to disrupt podocyte insulin responses early in the course of glomerular disease." (PMID 28852804, 2017). "The occurrence of type 2 diabetes amongst the pediatric population is assuming pandemic proportions, and has been linked with the growing burden of obesity, which disturbs the equilibrium between insulin secretion and sensitivity leading up to insulin resistance." (PMID 28109299, 2017). "If exogenous insulin use is associated with increased cancer risk, then an excess risk of cancer should be apparent in persons with type 1 diabetes, and this excess risk could potentially be larger than that observed in persons with type 2 diabetes." (PMID 26924393, 2016). "Type 2 diabetes mellitus (T2DM) is a multifactorial metabolic disorder characterized by chronic hyperglycemia caused by decreased production or sensitivity to insulin." (PMID 27833702, 2016). "In relation to type 2 diabetes, malathion causes an increase of intracellular Ca+2 in beta-cells, which could cause a loss of Ca+2/calmodulin-dependent protein kinase function that is involved in the regulation of insulin secretion." (PMID 27087124, 2016). "In particular, muscular fitness has been proven to be associated with insulin sensitivity in both children and adolescents which, in turn, is linked to the future risk of type 2 diabetes mellitus (T2DM) in adulthood." (PMID 26892886, 2016). "The adverse insulin response to the red meat/refined grain meal relative to the dairy/chicken/nuts/wholegrain meal indicates possible mechanisms through which these diets might affect risk of type 2 diabetes." (PMID 27809219, 2016).
type 2 diabetes (continued). "The primary cause for Huntington, Parkinson, Alzheimer, diabetes type 2 and Creuzfeld-Jajobs diseases, is the accumulation in, and outside cells of various misfolded conformers of specific proteins, such as huntingtin, Ataxin, alfa-synuclein, tau, insulin and PRPsc, respectively." (PMID 27508340, 2016). "While type 1 diabetes is caused by loss of insulin secretion due to destruction of pancreatic β-cells, progressive β-cell failure, including disruption of β-cell function and reduction of β-cell mass, is the central component of the onset and progression of type 2 diabetes." (PMID 26779540, 2016). "Type 2 diabetes (T2D) refers to a set of pathogenically distinct disorders which are usually identified by a persistent hyperglycemia, often due to a variable loss of the insulin-producing β cells of pancreas, and to a selective insensitivity to glucose of the residual β cells." (PMID 26959991, 2016). "Whether the combination of DPP-4 inhibition and insulin also minimizes glycemic variability is not completely known but would be important because glycemic variability may contribute to the long-term risk in type 2 diabetes." (PMID 26587020, 2015). "Studies have shown impaired insulin synthesis and secretion in animal models with vitamin D deficiency; diabetes onset can be delayed with 1–25-OH vitamin D intake, and some specific studies have reported that vitamin D deficiency contributes to the etiology and progression of type 2 diabetes." (PMID 26109389, 2015). "This study aims to undertake a targeted investigation into whether the common Ala12 allele modifies the association between objectively measured MVPA, sedentary time and markers of insulin sensitivity in participants with an increased risk of type 2 diabetes recruited from primary care." (PMID 25974167, 2015). "Type 2 diabetes has a complex relationship with breast cancer risk and outcome; coexisting obesity may be a major factor, but insulin itself induces adipose aromatase activity and estrogen production and also directly stimulates breast cancer cell growth and invasion." (PMID 26516917, 2015). "The proposed trial will provide much needed clinical evidence on the impact of excess dietary AGE consumption on insulin sensitivity and will indicate whether lowering dietary AGE intake can improve insulin sensitivity and/or secretion, thereby decreasing risk for type 2 diabetes." (PMID 26223897, 2015). "However, it is still unclear whether plasma MNA concentrations are associated with adipose tissue NNMT expression, impaired insulin sensitivity or type 2 diabetes in humans." (PMID 25596852, 2015). "However, haplodeficiency of Akt1 in Akt2-null mice exacerbates their insulin resistant phenotype to cause overt type 2 diabetes, thereby suggesting that Akt1 might also contribute to sustain glucose homoeostasis in mice." (PMID 25856301, 2015). "Although physiological roles of most miRNAs are largely unknown, recent evidence indicates that they are also associated with the regulation of insulin sensitivity for the treatment of type 2 diabetes and obesity, fat accumulation, and adipocyte differentiation." (PMID 24587298, 2014). "Given the link between glucose metabolism, mitochondrial function and insulin secretion in β-cells, and the reported association of PD with type 2 diabetes, we investigated the response of PINK1-deficient β-cells to glucose stimuli to determine whether loss of PINK1 affected their function." (PMID 24806840, 2014). "In addition to the influence of fiber and glycemic load on postprandial glucose and insulin response, whole grains may also reduce the risk of type 2 diabetes through the action of nutrients such as vitamin E and magnesium." (PMID 25192735, 2014).
type 2 diabetes (continued). "So far, type 2 diabetes associated genes identified through the many genome wide association studies performed during recent years have only explained a small fraction of the overall heritable risk for type 2 diabetes, and primarily been related to insulin secretion." (PMID 25148116, 2014). "Tight glycemic control with either intensive insulin therapy or sulfonylurea has been associated with weight gain in patients with type 2 diabetes (T2D)." (PMID 24650537, 2014). "HNF4α has been demonstrated to activate insulin gene expression indirectly via inducing the level of hepatic nuclear factor 1 and also directly through binding to a cis element of insulin promoter, and is recognized as a cause of maturity onset diabetes of the young, subtype 1." (PMID 25264921, 2014). "Thus use of insulin analogs may have dual effects in type 2 diabetes: decreasing cancer risk by improving metabolic control but simultaneously increasing cancer risk, because of its dose-dependent effects on cell growth and proliferation." (PMID 24904529, 2014). "Until now, associations of genetic polymorphisms at SIRT1 and FOXO1 with body mass index (BMI), visceral obesity, insulin sensitivity, type 2 diabetes mellitus (T2DM) and all-cause mortality risk have been described." (PMID 25273948, 2014). "Thus, if such dietary modifications can improve insulin sensitivity in at-risk groups, it may be possible to lower the incidence of type 2 diabetes, the metabolic syndrome, and cardiovascular disease in the general population." (PMID 25331725, 2014). "Importantly, type 2 diabetes is associated with impaired incretin-induced insulin secretion." (PMID 25373904, 2014). "The primary aim of this 6-month, double-blinded, placebo-controlled randomized trial was to evaluate whether combined calcium and vitamin D supplementation could improve insulin sensitivity, insulin secretion and β-cell function in vitamin D-deficient individuals at risk of type 2 diabetes." (PMID 25299668, 2014). "Type 2 diabetes (T2D) and insulin treatment may further result in doubling the risk for CRC." (PMID 25375205, 2014). "Therefore, the primary aim of the present study was to establish whether depressive symptoms are associated with time to insulin initiation in a sample of people with type 2 diabetes in primary care." (PMID 24223860, 2013). "It has also been discussed whether some patients display a mixture of phenotypes of type 1 and type 2 diabetes, which is sometimes referred to as “type 1.5 diabetes” or “double diabetes”, and require a therapy addressing insulin loss as well as insulin resistance." (PMID 24023937, 2013). "There is evidence to demonstrate that insulin is the antidiabetic agent with the greatest glucose-lowering capacity, and epidemio-logical studies have shown its benefits in terms of improving glycemic control and reducing the risk of long-term diabetic complications in type 1 and type 2 diabetes." (PMID 24223662, 2013). "The reduction in plasma HDL concentration and functionality associated with obesity and type 2 diabetes, may therefore be linked to impaired insulin sensitivity in skeletal muscle, which accounts for the majority of insulin-stimulated glucose disposal in the body." (PMID 23437184, 2013). "The aim of the present study was to investigate whether common and low-frequency variation in AGPAT6, encoding a novel GPAT enzyme, GPAT4, was associated with type 2 diabetes, obesity, dyslipidemia or indices of insulin resistance and insulin secretion in a large Danish population." (PMID 24156295, 2013). "Furthermore, whether insulin use in patients with type 2 diabetes may be associated with a higher incidence of HP eradication has not been investigated." (PMID 22571603, 2012).